FOXD4L4 (forkhead box D4 like 4)
Synonyms: FOXD4B; FOXD4L2; bA460E7.2; OTTHUMG00000013337; OTTHUMG00000066752
Tractability: No criterion of Open Targets' tractability assessment is met for any kind of drug.
Gene: Protein-coding gene on chromosome 9 (65,737,146 to 65,738,396, forward strand). Ensembl gene ENSG00000184659.
Subcellular location: Nucleus
Subcellular location (Human Protein Atlas): Nucleoplasm
Gene Ontology:
Molecular function: protein binding; DNA-binding transcription factor activity, RNA polymerase II-specific; RNA polymerase II cis-regulatory region sequence-specific DNA binding; DNA-binding transcription factor activity; sequence-specific DNA binding
Biological process: anatomical structure morphogenesis; cell differentiation; regulation of transcription by RNA polymerase II; regulation of DNA-templated transcription
Cellular component: chromatin; nucleus
Genetic constraint (gnomAD): Loss-of-function variants: 5 observed, 13.53 expected, observed/expected ratio (o/e) 0.37, 90% interval 0.19 to 0.78. The synonymous counts are far from expectation, so gnomAD's model fits this gene poorly and the ratio says little. Missense variants: 127 observed, 309.66 expected, observed/expected ratio (o/e) 0.41, 90% interval 0.35 to 0.47. Synonymous variants: 69 observed, 122.68 expected, observed/expected ratio (o/e) 0.56, 90% interval 0.46 to 0.69.
Homologues: Orthologues: mouse Foxd4 (50% identical). Paralogues in human: FOXD4L5 (99% identical), FOXD4L6 (98% identical), FOXD4L3 (98% identical), FOXD4 (84% identical), FOXD4L1 (71% identical), FOXD1 (33% identical), FOXD2 (31% identical), FOXD3 (30% identical), FOXE3 (25% identical), FOXC1 (23% identical), FOXE1 (22% identical), FOXC2 (22% identical), and 29 more.